INS (insulin)
Diseases named in the same sentence as INS in open-access papers (continued):
Sharing a sentence is not in itself a finding about the gene and the disease.
diabetes (continued). "However, some other human and animal studies showed lower levels of adipsin in type 2 diabetes, thus suggesting that this adipokine could increase insulin sensitivity and diminish glucose intolerance in patients with diabetes by its ability to enhance insulin secretion via C3a production." (PMID 39139157, 2024). "Previous studies have indicated that TG, HDL, LDL, TC, FPG, insulin, and HOMA-IR are effective indicators for predicting the diabetes mellitus in the general population." (PMID 38970008, 2024). "STZ is widely used as a type 1 diabetes mellitus (T1DM)-inducer in experimental animals, through its toxic effect on insulin producing β-cells." (PMID 39139399, 2024). "Fasting insulin and HOMA-IR are key indicators for assessing insulin resistance in patients with diabetes, while C-peptide levels reflect the secretory function of pancreatic β-cells." (PMID 39301316, 2024). "This is the first prospective study from sub-Saharan Africa describing the phenotype of adults newly diagnosed with diabetes who present with DKA and is one of few studies worldwide where insulin withdrawal was systematically attempted." (PMID 38240751, 2024). "Insulin initiation in older people with T2DM is an important step in achieving optimal glycaemic control and preventing diabetes-related complications." (PMID 39074147, 2024). "Hepatic steatosis had positive correlations with LSM, weight, BMI, ALT, AST, GGT, ALP, TG, hs-CRP, HbA1c, insulin, HOMA-IR, HOMA-IS, eGFR, smoking status, diabetes, and hypertension." (PMID 38721033, 2024). "This study provides a thorough examination of metabolic parameters, including glucose levels, insulin sensitivity, and markers of inflammation, offering a comprehensive understanding of the systemic effects of STZ-induced diabetes." (PMID 39337082, 2024). "Alternatively, hyperinsulinemia in early diabetes may play a more significant role than hyperglycemia in promoting cancer development because, after a particular diabetes stage, the progressive depletion of beta cell function leads to a steady decline in endogenous insulin production." (PMID 38751364, 2024). "Initial search phrases included combinations of key words such as “gut microbiome impact on insulin”, “Akkermansia effects on insulin sensitivity”, “microbiome modulation of GLP-1”, and “probiotics in diabetes treatment”." (PMID 39767626, 2024). "It serves as a glucose sensor, stimulating insulin secretion and being regulated by PPAR-γ, thereby playing a crucial role in β-cell reconstruction in patients with diabetes." (PMID 39734383, 2024). "Other scoring systems include the Hepatic Steatosis Index (HSI = 8 × ALT/AST ratio + BMI + 2 if diabetes, + 2 if female) and the NAFLD Liver Fat Score (based on metabolic syndrome, type 2 diabetes, fasting insulin, AST, and ALT)." (PMID 39339660, 2024). "Given the close relationships between puberty and disturbances in glucose and insulin secretion, it is advisable to carry out interventions before adolescence in order to reduce the early onset of IFG and diabetes." (PMID 40302960, 2024). "We used the mean value and standard error of AUC-insulin/AUC-glucose and the Matsuda index in 3 groups (NGT, prediabetes, diabetes mellitus)." (PMID 38188453, 2024). "DM, simply called diabetes, is a serious, long-term (or “chronic”) condition that is characterized by raised blood glucose levels because the body cannot produce any or enough of the hormone insulin or cannot effectively use the insulin it produces." (PMID 37266052, 2023). "Their study proposed that SARS-CoV-2 could directly determine an impairment of insulin secretion, with consequent disruption of the metabolic control in people already suffering from diabetes mellitus or leading to the development of new-onset diabetes mellitus." (PMID 37234545, 2023).
diabetes (continued). "In response to these findings, it is understood that diabetes control may be more difficult over the years, due to increasing risks and treatment overload, such as the progressive reduction in the reserve of β cells and C-peptide secretion, and reduction of insulin sensitivity." (PMID 37766694, 2023). "Type 1 diabetes mellitus (T1DM) is insulin-dependent and develops because of pancreatic beta-cell destruction which leads to insufficient insulin secretion." (PMID 36860368, 2023). "It has already been found that in the muscle tissue (myotubes) in case of diabetes there is a reduced primary flow of the TCA cycle, a condition that also characterizes the insulin-resistant offspring of patients with type 2 diabetes." (PMID 37762025, 2023). "Although ZFAND6 and PRC1 were identified as diabetes related loci in western populations, only recently the role of ZFAND6 and PRC1 loci have been described in insulin secretion and beta cell function through animal models." (PMID 37738238, 2023). "Diabetes, classified as type 1 diabetes mellitus (T1DM) and type 2 diabetes mellitus (T2DM), is a metabolic disorder accompanied by insufficient insulin production or insulin resistance." (PMID 36966186, 2023). "These functions are similar to its basic mechanism of anti-diabetes and are related to activating SIRT1 and insulin-related signaling pathways." (PMID 37009462, 2023). "Lately, several advances have been made in diabetes technology with the advent of smart insulin pens, CGMS and insulin pumps which have revolutionized insulin treatment, especially in patients with T1DM." (PMID 36845885, 2023). "Diabetes mellitus (DM) is a metabolic disorder characterized by hyperglycemia and glucose intolerance, which are related to defects in insulin secretion and/or the reduced effect of insulin on glucose uptake in peripheral tissues such as skeletal muscle, adipose tissue, and the liver." (PMID 37189497, 2023). "In Type 2 diabetes mellitus (T2DM), the body develops resistance to insulin, and despite having adequate or increased levels of this hormone, it becomes less effective at managing blood glucose levels." (PMID 38203517, 2023). "For diabetes, an insulin drip is started as needed (see ISR 1-120 BICU Insulin Clinical Practice Guidelines)." (PMID 39600024, 2023). "On the other hand, treatment for Type 2 diabetes mellitus (T2DM) consists of antidiabetic agents and insulin as basal, basal plus, or basal bolus administration." (PMID 36676765, 2023). "DM results mainly from insufficient insulin secretion or insulin resistance and exists in two main types: insulin-dependent diabetes mellitus (IDDM) (Type I) and non-insulin-dependent diabetes mellitus (NIDDM) (Type II)." (PMID 36984840, 2023). "Similarly, for pharmacologic treatment, we measured five to eight items: whether providers added, continued, switched, or stopped diabetes- (metformin, insulin, sulfonylurea, SGLT2i, GLP1 RA) and CV- (statin, antihypertensive) related drugs at least half the time." (PMID 37438853, 2023). "The keywords diabetes remission, Bariatric surgery, metabolic surgery, lifestyles, usual care, GLIP-1 agonists, insulin use, gastric banding, biliopancreatic diversion, sleeve gastrectomy, and Roux-en-Y gastric bypass, were used." (PMID 36829204, 2023). "Type 2 diabetes mellitus (T2DM) is characterized by elevated blood sugar levels (hyperglycemia), resistance to insulin, and reduced insulin secretion." (PMID 38161783, 2023). "The median age at diabetes diagnosis was 28 (IQR 24) years and 60% of patients needed insulin at diagnosis which is in line with literature." (PMID 36793123, 2023). "There were significantly more patients with diabetes mellitus in the NPWTi‐d group (35 vs. 17, p = 0.014, FET), although the insulin intake was similar between the groups (p = 0.151, FET)." (PMID 37465238, 2023). "On the 30th day of life, he was diagnosed with diabetes (BGL up to 23.8 mmol/L), and insulin therapy was started." (PMID 36398453, 2023).
diabetes (continued). "For insulin pumps in particular, pump cost prevents more universal uptake of CSII, which is regarded the gold-standard for glucose control and diabetes outpatient care." (PMID 37779821, 2023). "In summary, we report the discovery that CDK4 promotes insulin signaling and FOXO1 degradation in the pancreatic β cell, derepressing Pdx1 expression and rescuing diabetes in Irs2–/– mice." (PMID 37712417, 2023). "Notwithstanding, human data on CRP and insulin secretion are limited, as only one cross-sectional study found a link between CRP and impaired insulin secretion in a non-diabetes population." (PMID 37891561, 2023). "PTS modulates blood sugar levels, improves insulin response and lipid profiles, and reduces inflammation and oxidative damage in rats with diet-driven obesity and STZ-triggered diabetes by utilizing the PI3K/Akt signaling route." (PMID 38259272, 2023). "Information about insulin detemir in GDM is scarce and originates mainly from studies on pregestational diabetes, T1DM, or T2DM or both pregestational and gestational diabetes." (PMID 37775682, 2023). "These inflammatory factors have been confirmed to have a negative effect on insulin production, secretion and insulin signaling pathway, which may induce programmed cell death of pancreatic β cells, and aggravate the risk of IR and diabetes." (PMID 38273819, 2023). "Specific to diabetes prevention, a recent meta-analysis demonstrated that HIIT leads to greater improvements in insulin resistance compared with training at moderate intensity." (PMID 37998439, 2023). "Actually, the presented model is integrated with a liver model and a model representing insulin pharmacokinetics and runs on a mobile app to predict glucose dynamics after consuming a mixed meal and assess whether carbohydrate counting improves in people who live with diabetes." (PMID 37228105, 2023). "Diabetes mellitus (DM) is a group of metabolic disorders characterized by hyperglycemia Diabetes mellitus (DM) is a group of metabolic disorders characterized by hyperglycemia resulting from defects in insulin secretion, action or both”." (PMID 36973400, 2023). "Type 2 diabetes mellitus (T2DM) stands as a persistent ailment distinguished by the presence of elevated blood glucose levels, often stemming from a shortage in insulin secretion or complications related to pancreatic function." (PMID 38002152, 2023). "There are two types of diabetes: in type 1 diabetes mellitus (T1DM), the immune system attacks and kills the pancreatic β-cells that produce insulin, while in T2DM, insulin resistance develops." (PMID 37371692, 2023). "The benefits of the newer antidiabetic agents available for managing type 2 diabetes mellitus (T2DM) remain indisputable, but many patients will require insulin therapy in the disease course." (PMID 37132569, 2023). "Current diabetes treatment includes Sulfonylureas, Thiazolidinediones, Glinides, GLP-1 receptor agonists, DPP-4 inhibitors, insulin therapy, and SGLT2 inhibitors." (PMID 37240813, 2023). "Apart from fasting insulin, HbA1c and OGTT are routinely performed to screen for diabetes and are performed in a clinical setting." (PMID 37375611, 2023). "In terms of diabetes treatment, a higher frequency of subjects with DR were treated with both oral antidiabetic drugs (OAD) and insulin (p < 0.001)." (PMID 36904168, 2023). "The pancreas is a key site for regulating the secretion of insulin and glucagon, and an HFD can have an impact on the pancreas, leading to the development of diabetes." (PMID 36839280, 2023). "Moreover, studies have demonstrated that diabetes is an independent risk factor for MCI, with a complex mechanism, which may be related to impaired insulin signal transduction, inflammation, accumulation of advanced glycation end-products, and oxidative stress." (PMID 37814226, 2023).
diabetes (continued). "Despite overwhelming evidence in favour of TNF-α having a critical role in regulating inflammation and insulin-action, the translation of basic research findings with TNF-α-targeted neutralisation in diabetes showed disappointing results." (PMID 37627482, 2023). "In a different study, a rat model of type 2 diabetes mellitus with insulin resistance was used to test the anti-diabetic effects of CK, and the results showed that CK could increase food intake, body weight, insulin sensitivity, and fasting serum insulin level in diabetic rats." (PMID 37511939, 2023). "Outpatient use of diabetes technologies, particularly continuous glucose monitoring (CGM) and automated insulin delivery (AID) systems, rapidly expanded and has generated significant interest in its translation into the hospital setting." (PMID 37578778, 2023). "Trial duration contributed to the heterogeneity in the results of fasting blood glucose and HbA1c and diabetes type specified contributed to the heterogeneity in HOMA-IR and serum insulin level." (PMID 35946077, 2023). "Before, SAP therapy was a crucial advancement in diabetes treatment but, currently the development of CLC insulin delivery systems has been dramatically gaining clinical importance." (PMID 37574494, 2023). "Type 2 diabetes mellitus (T2DM) is a chronic metabolic disorder characterized by high blood sugar levels and decreased insulin secretion and sensitivity." (PMID 37740187, 2023). "We propose EDEM1 as a regulator of the UPR via IRE1/XBP1s and IRE1/JNK/c-Jun signaling cascades and insulin transcription in pancreatic β-cells, supporting EDEM1 as a potential target for the treatment of diabetes." (PMID 37822496, 2023). "The two main classifications of DM, namely type 1 diabetes (T1D) and type 2 diabetes (T2D), differ in that T1D consists of reduced insulin production; nevertheless, T2D consists of inadequate cellular response to insulin signaling." (PMID 38666042, 2023). "Type 2 diabetes mellitus (T2DM) is characterized by insulin resistance and/or defective insulin production in the human body." (PMID 38132335, 2023). "GLP-1 receptor agonists are a class of novel anti-diabetes agents and share similar effects of GLP-1, including glucose-dependent enhancement of insulin secretion and islet B cells proliferation." (PMID 36637917, 2023). "Extensive studies in diabetes over the past decade have shown that FOX factors are highly expressed in the brain, which are likely to be mediated by decreased sensitivity to insulin." (PMID 37396164, 2023). "Thus, hyperinsulinemia may prevent frank diabetes in insulin-resistant individuals." (PMID 36901984, 2023). "DM is differentiated as type I (insulin-reliant) and type II diabetes (insulin resistance)." (PMID 36839915, 2023). "One of the main types of diabetes is type 2 diabetes mellitus (T2DM), in which the body cells cannot respond to insulin, thus increasing blood sugar levels." (PMID 37970376, 2023). "Understanding insulin management approach options, and the potential impact on long-term metabolic outcomes, is a key component of promoting optimal post-TPIAT diabetes management." (PMID 37176759, 2023). "Diabetes mellitus (DM) is a metabolic disorder that leads to chronic hyperglycemia, a pathogenesis condition that may include defects in insulin secretion and/or action." (PMID 37240430, 2023). "By controlling CPT1A expression and enzyme activity, insulin can limit FAO and gluconeogenesis in order to lower blood sugar level, which is also one of the mechanisms to treat diabetes." (PMID 37033619, 2023). "The T2DM mice showed typical symptoms of diabetes, increased food and water intake, decreased weight gain, abnormal FBG and glucose tolerance, and decreased insulin levels." (PMID 37888727, 2023). "Data on the effect of MG53 on insulin signaling and type 2 diabetes mellitus (T2 DM) are still unknown; most are from preclinical studies." (PMID 37699054, 2023).
diabetes (continued). "Injectable peptides such as insulin, glucagon-like peptide 1 (GLP-1), and their agonists are being increasingly used for the treatment of diabetes." (PMID 37765234, 2023). "Wei reported that an insulin pump combined with UTI can shorten the recovery time of clinical symptoms and reduce the levels of inflammatory factors after diabetic ketoacidosis complicated with pancreatitis." (PMID 36800599, 2023). "The co-existence of type 1 diabetes mellitus (T1DM) and an ED has been termed “diabulimia,” and the core belief of these patients is that decreasing the daily dose of insulin is needed for losing weight or maintaining their current body weight." (PMID 37205977, 2023). "Diabetes technology including continuous glucose monitor (CGM), insulin pumps, and a combination of both, have become an important element in the management of diabetes." (PMID 40303258, 2023). "In the current study, we applied five parameters to represent diabetes severity, such as use of insulin and/or multiple OHAs, duration of DM ≥ 5 years, and the presence of CVD or CKD, and we found a significant association between the number of parameters and risk of TB." (PMID 37041513, 2023). "The pathophysiology of type 2 diabetes mellitus (T2DM) consists of insulin resistance and relatively decreased insulin secretion." (PMID 38115089, 2023). "According to the International Society of Pediatric and Adolescent Diabetes (ISPAD), T2D occurs in young individuals because of obesity, when insulin production becomes inadequate with respect to the increased demand due to IR (relative insulin deficiency)." (PMID 36980074, 2023). "While enhancing insulin sensitivity, growth-promoting properties of IGF-1 are proposed to play a role in developing complications of diabetes." (PMID 37438734, 2023). "According to previous studies, patients with diabetes and COPD faced difficulties of supplying medicine including insulin, scarcity of respirator masks, uncertainty of their ability to take medication and non-adherence to diet." (PMID 36871176, 2023). "Latent autoimmune diabetes in adults (LADA) is a type of diabetes mellitus showing overlapping characteristics between type 1 Diabetes Mellitus and type 2 Diabetes Mellitus (T2DM), and autoimmunity against insulin-producing pancreatic cells." (PMID 36758065, 2023). "The exact mechanism by which diabetes influences TSH is unclear, but since metformin use is associated with greater risk of lower TSH in hypothyroid patients, decreased blood glucose or increased insulin response could be responsible for connecting diabetes and ATD." (PMID 36793337, 2023). "High levels of inflammatory cytokines, in particular IL-6 and TNF-α, do not just cause reduced insulin sensitivity through the modulation of insulin signaling but also have pro-apoptotic effects on the β-cell contributing to the progressive failure in insulin secretion that ends in plain diabetes." (PMID 36980074, 2023). "Metformin, sulfonylurea, insulin, and thiazolidinediones (TZD) are the commonly used anti-diabetes medications." (PMID 36833075, 2023). "Type 1 diabetes mellitus (T1DM) is characterized by the death of β-cells, resulting in a definitive decrease in insulin output." (PMID 38132485, 2023). "Advancements in diabetes technology with insulin pump therapy, continuous glucose monitoring (CGM) systems and automated insulin delivery systems have revolutionised diabetes care." (PMID 37361523, 2023). "Although the non-surgical treatment included strict weight management, oral drug therapy and injection of insulin and GLP1, bariatric surgery is superior to reach diabetes remission and more significant reduction in BMI, HbA1c and FPG." (PMID 36810013, 2023). "The PDK4 level is elevated in patients with diabetes, and a PDK inhibitor enhances insulin activity by promoting glucose oxidation." (PMID 38104056, 2023).